CTSC (cathepsin C)
Diseases named in the same sentence as CTSC in open-access papers (continued):
Sharing a sentence is not in itself a finding about the gene and the disease.
Haim-Munk syndrome (9 papers, 2010 to 2022). Haim-Munk syndrome (HMS) is characterized by palmoplantar hyperkeratosis, severe early-onset periodontitis, onychogryposis, pes planus, arachnodactyly and acroosteolysis. "CTSC mutations have also been reported in patients with Haim–Munk syndrome (HMS, OMIM 245010), also characterized by palmoplantar hyperkeratosis and periodontal inflammation, as well as arachnodactly, acroosteolysis, pesplanus, and onychogryposis." (PMID 24936511, 2014). "Mutations in the CTSC gene, which encodes cathepsin C, have been identified as the underlying genetic defect in Haim–Munk syndrome and in the clinically related disorder, Papillon–Lefèvre syndrome, both of which are characterized by premature and severe periodontal disease." (PMID 23931052, 2013). "Through extensive literature analysis, we found that pathogenic variant of CTSC gene can lead to three closely related diseases: PLS, Haim‐Munk syndrome (HMS; OMIM 245010), and Aggressive periodontitis (AP1; OMIM 170650)." (PMID 33949806, 2021). "Recent investigations have illustrated that, like Haim-Munk syndrome, PLS can be caused by defects in cathepsin C gene located on the 11q14-q21 region of the chromosome." (PMID 23251811, 2012). "More than 75 different mutations in the CTSC gene may cause PLS, Haim–Munk syndrome, or prepubertal periodontitis, which are subsumed to the same phenotypical spectrum." (PMID 36554029, 2022). "Due to the implication of human cathepsin C in Papillon–Lefevre disease and Haim-Munk syndrome or inflammatory diseases, and the involvement of its malarial ortholog DPAP1 in the hemoglobin digestion pathway, both enzymes are considered interesting medical targets." (PMID 24381006, 2014).
hepatocellular carcinoma (9 papers, 2021 to 2024). A malignant tumor that arises from hepatocytes. "Recent evidence suggests that cathepsin C interacts with TNF-α/p38 mitogen activated protein kinase (MAPK) signaling pathways to promote hepatocellular carcinoma proliferation and metastasis." (PMID 37035802, 2023). "In hepatocellular carcinoma cells, CTSC accelerates proliferation and metastasis by activating the TNF-α/p38 pathway." (PMID 34326696, 2021). "In hepatocellular carcinoma, CTSC increases proliferation of cancer cells and migration and decreases apoptosis." (PMID 34737793, 2021). "In hepatocellular carcinoma, on the one hand, TNF-α can activate cathepsin C, and, on the other hand, cathepsin C can also activate the TNF-α/p38MAPK pathway, which has a close relationship with the growth of hepatocellular carcinoma." (PMID 37398678, 2023).
asthma (8 papers, 2012 to 2026). "In severe asthma (SA) and uncontrolled asthma (UA), increased secretion of Cathepsin C by airway epithelial cells activates the epithelial-mesenchymal transition unit (EMTU) via p38-mediated pathways, thereby promoting airway remodelling." (PMID 41573715, 2025). "On this basis, the expression of CTSC in the induced sputum of patients with asthma was verified, and the correlation between the expression of CTSC and lung function/airway remodeling parameters was analyzed, separately." (PMID 39436705, 2024). "Previous results of gene expression profiles (GSE19187 and GSE63142) showed that the expression of CTSC increased markedly in the epithelial cells of patients with asthma." (PMID 39436705, 2024). "In summary, this study has demonstrated that the increased expression of CTSC in the airway epithelia of patients with asthma induces airway remodeling through enhanced activation of EMTUs and aggravation of airway inflammation." (PMID 39436705, 2024). "The expression level of CTSC is positively related to the degree of airway remodeling in patients with asthma." (PMID 39436705, 2024). "Based on the dual role of CTSC in airway inflammation and airway remodeling, the study provides a new treatment for severe asthma or uncontrolled asthma." (PMID 39436705, 2024). "Increased expression of CTSC in AECs promotes EMTU activation in asthma models with airway remodeling." (PMID 39436705, 2024). "Both clinical and animal studies demonstrated the increased expression of CTSC in AECs of patients with asthma." (PMID 39436705, 2024). "Increased secretion of CTSC in airway epithelia induces airway remodeling in asthma through enhanced activation of EMTU by the p38-mediated signaling pathway." (PMID 39436705, 2024). "In this study, our clinical results demonstrated that the expression of airway remodeling–related protein CTSC increased markedly in the AECs of patients with asthma, which was a potential biomarker of SA." (PMID 39436705, 2024). "In this study, using a bioinformatics approach, our results found that the increased expression of CTSC in epithelia was most pertinent to airway remodeling in patients with asthma." (PMID 39436705, 2024). "Several asthma related genes were prioritized including SERPINB2 and CTSC genes, which showed functional relevance in multiple tissue/cell types and related to asthma pathogenesis." (PMID 37438356, 2023). "First, the expression and secretion of CTSC in AECs or air-liquid interface from patients with asthma cannot be verified in the clinic owing to the difficulty of obtaining bronchial mucosal tissue in patients with asthma." (PMID 39436705, 2024). "Increased expression of CTSC induces airway inflammation in asthma models." (PMID 39436705, 2024). "Moreover, a recombinant mouse CSTC protein–challenged (rmCTSC-challenged) model and two different asthma models with airway remodeling were employed to investigate the effect of CTSC on airway remodeling, EMTU activation, and airway inflammation." (PMID 39436705, 2024). "Moreover, compared with MMA or controlled asthma, the increase of CTSC in the airway or nasal epithelium of SA or UA was more marked." (PMID 39436705, 2024). "Our clinical results further demonstrated that the expression of CTSC was positively correlated with the parameters of airway remodeling in patients with asthma, which may be a potential predictive biomarker of patients with SA." (PMID 39436705, 2024). "Increased expression of CTSC induces airway remodeling in asthma models." (PMID 39436705, 2024). "Notably, the level of CTSC was negatively correlated with FEV1% and FEV1/FVC and positively associated with the wall area and the percentage of wall area of patients with asthma." (PMID 39436705, 2024).
asthma (continued). "Our studies demonstrated that the increased expression of CTSC in the airway epithelia of patients with asthma could induce airway remodeling by activating EMTU in the absence of obvious inflammation, which is consistent with our previous research and parallel studies." (PMID 39436705, 2024). "AZD7986, a potent Cathepsin C inhibitor, prevents airway remodelling and inflammation in HDM-induced asthma mouse models." (PMID 41573715, 2025). "Targeting CTSC through AZD7986 prevents airway remodeling and airway inflammation in the HDM-induced asthma model." (PMID 39436705, 2024). "Our results have shown that the increased expression of CTSC also promoted the infiltration of inflammatory cells and the production of inflammatory factors (e.g., IL-5, IL-13, and IL-17A) in the HDM-induced asthma model and SA model." (PMID 39436705, 2024). "Using bioinformatics analysis screening, we found that the expression of cathepsin C (CTSC; also known as dipeptidyl peptidase 1 [DPP-1]) increased markedly, which is most pertinent to airway remodeling of patients with asthma." (PMID 39436705, 2024). "Genetic inhibition of CTSC suppressed EMTU activation and airway remodeling in two asthma models with airway remodeling." (PMID 39436705, 2024). "IPA analyses of increased abundance of the four proteins (MMP9, AGT, S100A8, CTSC) in the POLD group (when compared to PTc) suggested increased neutrophil accumulation, which is a reasonable hypothesis given the association of neutrophilic inflammation with wheezing in asthma." (PMID 37474963, 2023). "Consequently, targeting CTSC with compound AZD7986 effectively suppressed airway inflammation and remodeling simultaneously in the HDM-induced asthma model." (PMID 39436705, 2024). "Consequently, targeting CTSC with compound AZD7986 protected against airway inflammation, EMTU activation, and remodeling in the asthma model." (PMID 39436705, 2024). "Additionally, we found that the association effect estimates of cold were significantly higher among participants with asthma compared with non-asthmatic participants for four proteins (AGRE2, CTSC, EIF5A, and NBN)." (PMID 41541696, 2026).
COVID-19 (8 papers, 2020 to 2025). A disease caused by infection with severe acute respiratory syndrome coronavirus 2. "However, the rs592381 A allele (risk allele in European populations) also showed significant association with higher expression of CTSC in whole blood tissues (P = 1.2 × 10−7) from QTLbase, which also suggested a risk role for CTSC in the COVID-19 severity." (PMID 34465742, 2021). "Finally, potential therapeutic targets were implicated in the current study, including CTSC, which may benefit the treatment of COVID-19." (PMID 34465742, 2021). "For cathepsin C IHC results, the median of controls was 1+, while the median of COVID-19 patients was 3+ (p < 0.0001)." (PMID 35326463, 2022). "Taken together, these pieces of evidence suggested a strongly biological plausibility for CTSC in the development of COVID-19." (PMID 34465742, 2021). "Interestingly, our analysis found the gene CTSC to be upregulated in lung tissue of deceased COVID-19 patients." (PMID 35326463, 2022). "Taken together, these results suggested a potential role for CTSC in the development of COVID-19." (PMID 34465742, 2021). "Moreover, published clinical trials showed that intravenous α1AT or inhibition of cathepsin C, a dipeptidyl peptidase required for the maturation of NSPs into active enzymes, did not improve the clinical course of hospitalized COVID-19 patients." (PMID 38470488, 2024).
colorectal cancer (7 papers, 2014 to 2025). A primary or metastatic malignant neoplasm that affects the colon or rectum. "Previous studies have also demonstrated that CTSC was aberrantly expressed in various tumors, such as glioma, colorectal cancer, and liver cancer, and was closely associated with worse patient prognosis." (PMID 40740774, 2025). "Therefore, decreased CTSC expression causes an unfavorable environment for the survival of colorectal cancer cells." (PMID 36831614, 2023). "CTSC was associated with proliferation of colorectal cancer cell, but this gene may be responsible for the proliferation of GBM cells." (PMID 31137733, 2019). "Silencing CTSC has the capacity to promote apoptosis, thereby restraining the growth of colorectal cancer." (PMID 38742112, 2024). "We demonstrated that HA1 suppresses autophagy and regulates the cell cycle by inhibiting CTSC in colorectal cancer." (PMID 36831614, 2023). "Moreover, HA1 reduced the expression of CTSC, which is high in colorectal cancer and other carcinomas, thereby inhibiting cell growth and causing cell cycle arrest." (PMID 36831614, 2023).
glioma (7 papers, 2021 to 2025). A benign or malignant brain and spinal cord tumor that arises from glial cells (astrocytes, oligodendrocytes, ependymal cells). "The expression of CTSC positively correlated with the grade of glioma and closely associated with the noncoding status of 1p/19q and wild-type IDH genotype." (PMID 35109832, 2022). "Our results confirm that high expression of CTSC in gliomas can shorten survival time of patients, and is related to the malignant clinical characteristics of gliomas, which can be used as an independent risk factor of gliomas." (PMID 35109832, 2022). "This study found that the inhibition of CTSC increases cell senescence and the expression of CTSC is associated with poor prognosis of glioma patients." (PMID 33946049, 2021). "To explore whether the level of CTSC expression is associated with the prognosis of patients with glioma, we analyzed clinical samples from three databases, namely, CGGA RNA-seq, CGGA microarray, and TCGA RNA-seq." (PMID 35109832, 2022). "The multivariate analysis showed that high CTSC expression might be an independent risk factor for poor prognosis in patients with glioma." (PMID 35109832, 2022). "Indeed, high expression of CTSC was associated with poor prognosis in glioma cases." (PMID 33946049, 2021). "Recent bioinformatics-based screening has identified CTSC as a potential candidate since knock-down of CTSC has been found to be able to increase cell aging in glioma cell lines." (PMID 37208656, 2023). "In their experiment, glioma cells were treated with piperlongumine and scopoletin separately, and the results showed that the synthesis of CTSC was significantly inhibited." (PMID 37398678, 2023). "The expression of CTSC in glioma and its relationship with clinical characteristics and prognosis of patients with glioma were analyzed at different levels by using clinical sample information from several databases." (PMID 35109832, 2022). "The results of this study expand the molecular biological function of CTSC, reveal the development mechanism of glioma from a new perspective, and provide a potential biomarker for the prognosis of glioma." (PMID 35109832, 2022). "We found that CTSC protein expression in glioma samples was higher than that in normal brain tissues." (PMID 35109832, 2022). "In the clinical brain tissue samples collected by us, the expression of CTSC in 23 patients with glioma was higher than that in 9 normal brain tissue samples (P < 0.05)." (PMID 35109832, 2022). "In this study, we used data from public databases to reveal the role of CTSC in the malignant progression of glioma and analyzed the possibility of using CTSC expression level for glioma prognosis." (PMID 35109832, 2022). "We found that compared with its level in normal human astrocytes, the CTSC expression level in glioma cell lines was significantly (>twofold) higher, with the highest, fourfold increase being observed in LN-229 cells (P < 0.05)." (PMID 35109832, 2022). "We comprehensively analyzed data from multiple databases and for the first time revealed a role and specific mechanism of action of CTSC in glioma, identifying it as a novel and efficient biomarker for the diagnosis and treatment of this brain tumor." (PMID 35109832, 2022). "In particular, by using the CMap analysis, we identified two small-molecule compounds, PL and SCO, that inhibited CTSC mRNA expression in glioma cells as was confirmed by RT-qPCR." (PMID 35109832, 2022). "Further, the analysis of multiple datasets in the GEO database also showed that CTSC was overexpressed at the molecular level in glioma." (PMID 35109832, 2022). "The latest report has confirmed that aging-related genes do have an impact on glioma, including CTSC." (PMID 35109832, 2022). "The key role of genes co-expressed with CTSC in malignant tumors (including glioma) has also been widely studied." (PMID 35109832, 2022).
glioma (continued). "The high expression of BAI3 indicates a relatively better prognosis for patients with glioma, which also indirectly provides evidence for a positive correlation between high CTSC expression and glioma malignancy." (PMID 35109832, 2022). "In this study, we investigated the clinical significance of the CTSC expression pattern in gliomas of different grades." (PMID 35109832, 2022). "We found that the survival of patients with glioma that had high CTSC expression was shorter than of patients with low CTSC expression (P < 0.001)." (PMID 35109832, 2022). "CTSC expression levels in glioma and normal brain tissues, as well as in glioma cells and normal brain cells, was validated by real-time quantitative polymerase chain reaction (RT-qPCR)." (PMID 35109832, 2022). "In this study, we found increased expression of CTSC in glioma based on the data from the GEPIA database." (PMID 35109832, 2022). "Next, we verified the CTSC expression level in clinical glioma samples and laboratory glioma cell lines by RT-qPCR." (PMID 35109832, 2022). "To study the effect of the CTSC gene on cell senescence in glioma cells, we knocked-down the CTSC gene in SHG-44 cells and U251 cells using siRNA-623, siRNA-837 and siRNA-963." (PMID 33946049, 2021). "Knock-down of CTSC, an aging-related gene, can inhibit cell cycle progression, colony formation, cell proliferation and increase cell senescence in glioma cell lines in vitro." (PMID 33946049, 2021). "To explore the effect of CTSC expression on the survival of glioma patients, we compared the OS, PFI, and DSS of cases from TCGA and CGGA datasets based on the expression of CTSC." (PMID 33946049, 2021). "Our study confirmed the targeted inhibition of CTSC expression in glioma cells by PL, which may be the key mechanism by which PL inhibited the malignant progression of glioma." (PMID 35109832, 2022). "The connectivity map was used to reveal small molecules that may inhibit CTSC expression in glioma, and the putative effect of these compounds was verified by RT-qPCR." (PMID 35109832, 2022). "In addition, researchers have also found that BAI3, a gene whose expression negatively correlated with that of CTSC, was expressed less in glioma than in normal brain tissue." (PMID 35109832, 2022). "In our study, we focused on the expression of CTSC in glioma and its relationship with the prognosis of patients with glioma, but we did not further study the signaling pathways through which high CTSC expression affected the malignant process of glioma." (PMID 35109832, 2022). "CTSC may serve as an efficient molecular target for the diagnosis and therapy of glioma, thereby improving the poor prognosis of patients with glioma." (PMID 35109832, 2022). "Our research is the first to use clinical sample data from multiple databases to comprehensively and systematically analyze and reveal the correlation of CTSC expression pattern in glioma, with the aim of identifying a new target marker for the diagnosis and prognosis of this cancer." (PMID 35109832, 2022). "Moreover, the protein expression of CTSC in high-grade glioma was higher than that in low-grade glioma." (PMID 35109832, 2022). "GSEA showed that CTSC expression may regulate the malignant development of glioma through Toll-like receptor signaling pathways, pathways in cancer, and extracellular matrix receptor interaction signaling pathways." (PMID 35109832, 2022). "Our results suggest that CTSC may be a novel prognostic marker and a potential antitumor target for the treatment of glioma." (PMID 35109832, 2022). "Therefore, piperlongumine and scopoletin may have potential as drugs targeting CTSC for the treatment of glioma." (PMID 37398678, 2023). "Therefore, we speculate that CTSC might participate in the pathological process and malignant progression of glioma." (PMID 35109832, 2022).